NF1 (neurofibromin 1)
Diseases named in the same sentence as NF1 in open-access papers (continued):
Sharing a sentence is not in itself a finding about the gene and the disease.
tumor (continued). "When adjusted for age, gender, and tumor type in a multivariable Cox regression model, with the BRAF group as the reference group, the NF1 subtype still had the worst DSS (P = 0.03) and OS (P = 0.06)." (PMID 28267273, 2017). "The percentage of NF1 and MPNST specimens exhibiting biomarker positivity (or in case of Ki67 staining, percentage of specimens exhibiting positive staining in ≥ 10% of tumor cells) was calculated." (PMID 29285213, 2017). "Maertens and colleagues have identified increased activation of the PI3K/AKT/mTOR pathway in BRAF/NF1 double mutants, and a combinatorial MEK marker and mTOR inhibitor treatment has proven effective in many MEK inhibitor-resistant neoplasms." (PMID 28637487, 2017). "Diagnosis of NF1-related MPNST should be based on converging criteria, including clinical symptoms, imaging, histopathology, and, at times, tumor genotype." (PMID 26445379, 2015). "Four of the models are patient-derived tumor xenografts (PDTX), two independent MPNSTs from the same NF1 patient and two from different sporadic patients." (PMID 25810463, 2015). "Somatic mutations in inherited PCC/PGL genes can be detected in ~25–30% of the sporadic tumours (mainly involving RET, VHL, NF1, MAX, and HIF2A genes)." (PMID 25883647, 2015). "This would help to explore further the relationship with NF1 of not only SPP1 but the other identified statistically significant genes, which are differentially expressed between benign and malignant NF1 tumours." (PMID 25884485, 2015). "Interestingly, the Grb10 gene localizes to a region involved with LOH, suggesting that genetic loss of the expressed Grb10 allele may underlie the absence of Grb10 transcripts in Nf1 mutant tumor cell lines." (PMID 26000738, 2015). "We showed that the concurrent knockdown of PKC α and β triggered apoptosis in the cells with Nf1 defect, in which PKC δ acted as a tumor suppressor for inducing apoptosis." (PMID 25301738, 2014). "Knockdown of miR-193b in HNSCC cells increased NF1 transcript and protein expression levels, decreased ERK phosphorylation with reduction in cell viability, migration, invasion and tumour formation." (PMID 25026295, 2014). "Transcription factors NF1 and AP1 also committed important roles in the regulation of progenitor cells in tumor initiation." (PMID 24222909, 2013). "In summary, we have identified a novel oncogenic role for miR-193b, whereby high miR-193b suppresses NF1, in turn activating p-ERK, leading to increased HNSCC cell proliferation, invasion, migration, and tumour formation." (PMID 23335975, 2013). "Third, midkine, a ligand that activates mammalian ALK, is produced by NF1−/− Schwann cells, present at elevated levels in NF1 patient skin and serum, and acts as a mitogen for NF1 tumor cell lines." (PMID 24278035, 2013). "ZEB1 positive tumours showed a significant enrichment for PCNA and EGFR, while NF1 deletions were significantly more prevalent in ZEB1 negative specimens." (PMID 23818228, 2013). "Whole genome shotgun sequencing detected the rearrangements involving several known tumor suppressors in 20 tumor/normal sample pairs, which were further confirmed by RNA sequencing including PTEN, RB1, NOTCH1, NF1, and CDKN2A." (PMID 23109866, 2012). "The only NF1 patient, who developed an MPNST in our previous longitudinal study of internal tumours using local 2-dimensional MRI measurements was also the only adult in that study whose tumour exhibited rapid growth." (PMID 23035791, 2012).
tumor (continued). "The overall similarity in tumor burden among these conditions is striking given the diverse functions of the NF1, NF2, and SMARCB1 tumor-suppressor genes." (PMID 22558206, 2012). "Provided that this correlation can be confirmed in a larger cohort of NF1 patients, MIA would be a valuable biomarker for the internal tumour load." (PMID 21726432, 2011). "Unfortunately our unique case report raises more questions than provides answers because there are very few cases of NF-1-related concurrent GEP NE tumours and GISTs and also very little understanding of the prognostic implications of such concurrent tumours." (PMID 19216788, 2009). "EGFR expression by tumour cells was detected byimmunohistochemistry in 36 out of the 42 (86%) valuable patients with MPNST;percentages were higher in the NF1 subgroup (95% versus 75%; P = .06; Chisquare test)." (PMID 18769552, 2008). "Interestingly, both NF1-positive patients were normotensive-one (c.3496G > A) with a non-secretory tumor and the other (c.2329T > A) presenting at an unusually late age (63 years)-a strikingly atypical spectrum that underscores the phenotypic variability of NF1-associated PPGL." (PMID 41598651, 2026). "To assess overall relationships, we included all samples for unsupervised clustering by gene expression, regardless of the Nf1 genotype or tumor type." (PMID 39804140, 2025). "Novel therapeutic strategies, including AAV-based gene therapy aimed at restoring NF1 function, oncolytic herpes simplex virus (oHSV) therapy targeting RAS-dysregulated tumor cells, and chimeric antigen receptor T cell (CAR-T) therapy targeting NF1-associated tumors, are under active investigation." (PMID 41374990, 2025). "We captured LOH-driven NF1 null clone sizes as small as 2% (PD51122b; cerebellum) and up to 13% (PD51122h_lo0012; occipital cortex), and no second NF1 hit was related to a neoplasm." (PMID 40000831, 2025). "We hypothesize that in newly diagnosed NF1-altered GBM patients, inhibition of RAS-RAF-MAPK-induced migration, together with local treatment, could improve tumor control and survival." (PMID 40575417, 2025). "These include a high tumor mutational burden (46 mutations per Mb), the presence of NRAS and NF1 mutations, and the absence of BRAF V600E mutations." (PMID 40125165, 2025). "In the subgroup of non-NF-1 OPG, however, a minor, thus significant correlation of tumor growth and change of logMAR could be shown (R2 = 0.35, p = 0.04)." (PMID 40643687, 2025). "GBM may present mutations in genes involved in activated KRAS signaling, such as NF-1 (neurofibromin-1), indicating KRAS pathways as a potential target in this tumor." (PMID 40362343, 2025). "In the single-dose PK–PD study with tovorafenib in the NF1-LOF tumor model, a pERK increase was only observed at 24 hours and not at earlier time points." (PMID 40111124, 2025). "Previous studies from our laboratory revealed striking Nf1-OPG tumor dependence on non-neoplastic tumor cells and soluble mediators." (PMID 41497446, 2025). "Nevertheless, as opposed to the deletion of Nf1, for instance, the disruption of Cic only moderately enhances tumor initiation in our model." (PMID 41219537, 2025).
tumor (continued). "The survival analysis indicated that in NF1-associated MPNSTs, RASSF1A promoter methylation serves as a marker of a poor prognosis, independent of other clinical risk factors such as tumour size and metastasis." (PMID 40843672, 2025). "NGS of this tumor specimen was again negative for BRAF, KIT, NF1, and NRAS mutations, but was again notable for a missense mutation in EZH2 (c.2075 C > T, p.A692V)." (PMID 39984702, 2025). "Ultimately, while no single mouse model recapitulates all aspects of NF1, several robust models exist for studying specific symptoms and tumor types." (PMID 41294711, 2025). "In contrast, subtype C2 predominantly features mutations in genes involved in kinase signaling pathways, including NF1 and RET, which imply active signaling networks that could influence tumor growth and response to therapies." (PMID 41400463, 2025). "While tumours lacking variants in these genes but also BRAF/RAS and NF1 have been dubbed ‘quadruple wild-type’, it is more appropriate to specify those genes that have been tested, e.g. WT for KIT, PDGFRA, NF1 and BRAF/RAS." (PMID 38840030, 2025). "However, all treatments that reduced Nf1-OPG proliferation also exhibited decreased Neu4 and Gpr17 expression, suggesting similar effects of the various treatments on tumor cell content." (PMID 41497446, 2025). "First, NF1-OPG biology is dictated by the cooperative interactions of numerous non-cancerous cell types in the tumor microenvironment (TME)." (PMID 41497446, 2025). "The similar effects of the two inhibitors on gene expression in tumor glial cell populations likely reflect on-target pathway effects in tumor cells regardless of their Nf1 status, as cells with Nf1 knockout are a minority in this model." (PMID 40992926, 2025). "The tumor’s response to selumetinib did not affect other NF1-related features, such as CALMs, FASI, or Lisch nodules, all of which remained stable throughout treatment." (PMID 40271285, 2025). "Among several NF1-unrelated human xenograft tumors, which were subcutaneously implanted in mice with the exception of the 143B tumor which was implanted intra-tibially, AAV-K55-GFP did not exhibit significant transduction." (PMID 41022755, 2025). "In both NF1-LOF in vivo tumor models, there was no antitumor activity observed with tovorafenib at clinically relevant exposures." (PMID 40111124, 2025). "MEK and SHP2 inhibition each reduced tumor volume and depleted recruited macrophages; MEK inhibition also dramatically reduced macrophages and dendritic cells in PNF from individuals with human NF1." (PMID 40992926, 2025). "While MEKi show promise for NF1-related conditions, no direct comparison studies of their clinical efficacy, toxicity profiles, or impact on the tumor immune microenvironment have been conducted." (PMID 40725763, 2025). "Children with NF1 showed higher tumour response rates to the CV when compared to those without a NF1 genetic predisposition." (PMID 38299304, 2024). "No BRAF, NRAS, NF1 or TERT promoter mutations were detected, though all tumor samples harbored additional mutations." (PMID 38903495, 2024).
tumor (continued). "Capmatinib strongly inhibited tumor growth in both the NF1-MET and NF1-MET;sgP53 models, however only the NF1-MET tumors regressed on treatment (p-value = 0.0083), while the NF-MET;sgP53 tumors remained stable throughout treatment, with a subset of tumors actually showing increased growth." (PMID 38480916, 2024). "DNAm profiling classified this tumor as ERMS, which is in contrast with this hypothesis and supports the possibility that ERMS may arise in the context of NF1." (PMID 38178234, 2024). "Nf1-/- mice die of cardiac failure at embryonic day 13.5 and are thus not useful for studying PNF development or identifying the specific cell types responsible for tumor initiation." (PMID 38473354, 2024). "As expected, knockout (KO) of Nf1 or Tsc1 or Tgfbr2, but not Nf2, increased the number of spontaneous lung metastatic nodules and increased the primary tumor size." (PMID 38997291, 2024). "Concomitant Nf1 KO and Rason OE maximumly increased KRASG12D-induced MEF tumor formation." (PMID 36241718, 2023). "NF1 is a tumor suppressor gene coding for neurofibromin, a negative regulator of cell growth and proliferation via downstream activity of mitogen-activated protein kinase (MAPK) pathway." (PMID 37519788, 2023). "While we did not detect a mutation on the second allele of NF1, immunostaining for NF1 in an FFPE section from Sample 3 - I showed a discrete NF1-negative tumor area indicating loss of NF1 protein in this region." (PMID 37932252, 2023). "NF1 and EGFR co-altered samples thus may be phenotypically significant in tumor recurrence but rarely detected from the analysis of single biopsies or those originating from the resected portion of the CE tumor." (PMID 37770427, 2023). "Based on the histological features, although the patient did not have NF-1, the tumor was strongly suspected to be ANNUBP." (PMID 37252482, 2023). "Conversely, when the RTK/RAS pathway drives gliomagenesis (by NF1 inactivation and EGFR amplification in C3 and C4 models, respectively), the inferred tumor progression relies on the acquisition of PTEN alterations, and subsequent up-regulation of the PI3K pathway." (PMID 37770427, 2023). "Even the Nf1 mouse-derived MPC/MTT cell lines, the best characterized model system available, have no direct genetic relation to SDH-mutated human tumours." (PMID 36178902, 2022). "Tumor promotion by SHP-2 (G503V) and its suppression by BRAP (G370A) may serve as a basis for the development of new treatment strategies for NF1." (PMID 35625983, 2022). "NGS analysis of her GIST lesion revealed a quadruple wild-type tumor (no mutations in c-KIT, PDGFRA, SDH, RAS-P [RAS, BRAF, NF-1]) with a FGFR3 p.G145S mutation/variant which is of a germline rather than somatic variation." (PMID 35885469, 2022).
tumor (continued). "The recent criteria by the RAPNO working group emphasizes that especially in NF1 + OPG patients visual impairment rather than tumor growth is the most common symptom leading to therapy." (PMID 34994964, 2022). "Consistent with the lack of tumor formation, Arg1809Cys-mutant neurons do not induce Adam10-mediated cleavage and shedding of Nlgn3, a growth factor required for murine Nf1-OPG initiation and growth." (PMID 35589737, 2022). "NF1 protein is a tumor suppressor protein; impaired NF1 may increase the Ras activity and then activate the PI3K-Akt signal pathway, which regulates tumor cell growth, survival, and angiogenesis." (PMID 35559021, 2022). "Relevant to pediatric LGGs, like NF1-PA and BRAF-driven PAs, the derivative tumor cells undergo oncogene-induced senescence and display a senescence-associated secretory phenotype (SASP) in vitro unless provided with fibroblast conditioned medium and ROCK inhibition or senolytic inhibitors." (PMID 35986378, 2022). "Several patients were treated with small molecule MEK inhibitors that resulted in stable disease or tumor regression when used as a single agent, but only in the context of those tumors with NF1 inactivation lacking additional oncogenic alterations." (PMID 35945463, 2022). "Both NF-1 and anterior tumour position were more common in those 38/90 (42.2%) without EMD, of whom half (50%) had NF-1, 19 (21.1%) and 9 (10%) had MDC1 and MDC2, respectively, whilst only a minority (10: 11.1%) had MDC3/4." (PMID 35159015, 2022). "To further elicit better predictors amongst the range of PD-L1 expression in tumor tissues, we grouped the samples based on three genetic backgrounds: sporadic cases, pseudohypoxia cluster (SDHB, VHL, EGLN1, EPAS1) and kinase signaling cluster (RET, NF1)." (PMID 36439433, 2022). "While pilot-testing the abstraction platform, we found that the terms: “NF”, “Cafe-au-lait” and “sheath tumour” when found alone, were not related to NF1." (PMID 36028856, 2022). "Next, the Cox regression hazard model was performed using the following confounder variables: age, gender, tumor stage, type of tumor (primary/metastatic), and presence/absence of BRAF, NRAS, and NF1 mutations." (PMID 34502169, 2021). "At time of NF1 diagnosis, 53 patients (8.0%) had synchronous presentation of nonneurofibroma neoplasms." (PMID 33734413, 2021). "Interestingly, NF1, a negative regulator of the RAS/MAPK pathway almost solely comprised a second tumour signature, indicative of therapy response (AUC=1)." (PMID 35083152, 2021). "Similar copy number alterations were also observed in the parent tumor, although the observed copy number gain did not encompass the entire NF1 gene." (PMID 33707600, 2021). "We similarly identified more patients with a high tumor burden (> 3000 ml) in the NF1 whole gene deletion groups, but this difference was not statistically significant when compared to patients without large deletions of the NF1 gene." (PMID 33951044, 2021). "In NF1 related Schwann cell lines, they were stably expressed irrespective of tumor pathology and severity." (PMID 33630851, 2021). "In comparison, patients without large deletions of the NF1 gene did not display such an accentuated averaged annual tumor-growth at a young age." (PMID 33951044, 2021). "In NF1-null or silenced MES GBM, the microenvironment is heterogenous with a hypoxic core and perivascular niche, each secreting different cytokines and chemokines that drive tumour malignancy." (PMID 35008787, 2021).